RN7SL382P (RNA, 7SL, cytoplasmic 382, pseudogene)
Gene: Miscellaneous RNA gene on chromosome 4 (139,100,377 to 139,100,658, forward strand). Ensembl gene ENSG00000240723.
Homologues: Orthologues: chimpanzee Metazoa_SRP (97% identical), macaque Metazoa_SRP (93% identical). Paralogues in human: RN7SL1 (80% identical), RN7SL3 (79% identical), RN7SL2 (79% identical), RN7SL126P (78% identical), RN7SL14P (78% identical), RN7SL630P (78% identical), RN7SL679P (78% identical), RN7SL45P (77% identical), RN7SL197P (77% identical), RN7SL88P (77% identical), RN7SL478P (77% identical), RN7SL296P (76% identical), and 702 more.